NOMO1 (NODAL modulator 1)
Description:
Component of the multi-pass translocon (MPT) complex that mediates insertion of multi-pass membrane proteins into the lipid bilayer of membranes. The MPT complex takes over after the SEC61 complex: following membrane insertion of the first few transmembrane segments of proteins by the SEC61 complex, the MPT complex occludes the lateral gate of the SEC61 complex to promote insertion of subsequent transmembrane regions.
Synonyms: PM5; Nomo
Tractability: Antibody: UniProt predicts a signal peptide or a membrane-spanning region. PROTAC: ubiquitination databases record sites on it; its protein half-life has been measured.
Gene: Protein-coding gene on chromosome 16 (14,833,721 to 14,896,157, forward strand). Ensembl gene ENSG00000103512.
Subcellular location: Endoplasmic reticulum membrane
Subcellular location (Human Protein Atlas): Endoplasmic reticulum
Gene Ontology:
Molecular function: protein binding; ribosome binding; carbohydrate binding
Biological process: multi-pass transmembrane protein insertion into ER membrane
Cellular component: endoplasmic reticulum; endoplasmic reticulum membrane; membrane; multi-pass translocon complex
Genetic constraint (gnomAD): Loss-of-function variants: 38 observed, 90.91 expected, observed/expected ratio (o/e) 0.42, 90% interval 0.32 to 0.55. The synonymous counts are far from expectation, so gnomAD's model fits this gene poorly and the ratio says little. Missense variants: 397 observed, 933.01 expected, observed/expected ratio (o/e) 0.43, 90% interval 0.39 to 0.46. Synonymous variants: 200 observed, 349.09 expected, observed/expected ratio (o/e) 0.57, 90% interval 0.51 to 0.64.
Homologues: Orthologues: rat Nomo1 (93% identical), mouse Nomo1 (92% identical), tropical clawed frog nomo3 (78% identical), zebrafish nomo (69% identical), Drosophila melanogaster CG1371 (31% identical), Caenorhabditis elegans nra-4 (24% identical). Paralogues in human: NOMO3 (99% identical), NOMO2 (99% identical).
Diseases named in the same sentence as NOMO1 in open-access papers:
NOMO1 is named in the same sentence as 23 diseases in open-access papers, as found by Europe PMC text mining. Sharing a sentence is not in itself a finding about the gene and the disease. The quoted sentences say what the papers report.
colorectal cancer (4 papers, 2017 to 2024). A primary or metastatic malignant neoplasm that affects the colon or rectum. "A distinct molecular feature of EOCRC is that compared with cases of late-onset colorectal cancer, in EOCRC cases, there is a higher incidence of Nodal Modulator 1 (NOMO1) somatic deletions." (PMID 36011023, 2022).
acute myeloid leukemia (2 papers, 2019 to 2023). Acute myeloid leukemia (AML) is a group of neoplasms arising from precursor cells committed to the myeloid cell-line differentiation. "Under serum starvation conditions, acute myeloid leukemia (AML) Nomo-1 and Kasumi-1 cells with Gas6 and AXL silenced with two distinct shRNAs showed a two- to three-fold increase in apoptosis." (PMID 37265798, 2023).
autism (2 papers, 2013 to 2024). Persistent deficits in social interaction and communication and interaction as well as a markedly restricted repertoire of activity and interest as well as repetitive patterns of behavior. "Nomo1 deficiency results in autism-like behavior in zebrafish, associated with brain immune responses and disturbed serotonin/melatonin metabolism." (PMID 38253686, 2024). "NOMO1 is located at 16p13.11, multiple genetic analyses of large samples have shown that chromosomal segment 16p13.11 is strongly associated with neuropsychiatric disorders, suggesting a potential role for NOMO1 in neuropsychiatric disorders, particularly autism and epilepsy." (PMID 38253686, 2024).
malignant melanoma (2 papers, 2017 to 2022). "The most significant differences in melanoma are NOMO1, PIGT, VKORC1, PDIA5 and DDX11, and the most significant differences in uterine cancer are CTU2, EMC8, TUBG1, CLPP and LONP1." (PMID 34951103, 2022).
alcohol (1 paper, 2023). "We observe positive colocalization [posterior probability (PP) > 80%] for 5 of 18 proteins with the same traits (ADGRE2 and total cholesterol [TC]; ANGPTL7 and BMI, waist-hip ratio; ITGB7 and TC; NOMO1 and LDL, TC; SEMA3F and BMI, alcohol use), supporting the two-sample MR results." (PMID 37550624, 2023).
cervical cancer (1 paper, 2022). A primary or metastatic malignant neoplasm involving the cervix. "HMGA1, up-regulated in NOMO1-KO cells, is overexpressed in cervical cancer tissues and is positively correlated with lymph node metastasis and advanced clinical stage." (PMID 36011023, 2022).
colon cancer (1 paper, 2022). "Our results indicate that NOMO1 loss could be a passenger mutation in the development of EOCRC, although it contributes significantly to colon cancer cell migration." (PMID 36011023, 2022). "In conclusion, our data suggest that, despite being deleted in 70% of EOCRC cases and promoting colon cancer cell migration, NOMO1 might play a secondary role in the development of this disease." (PMID 36011023, 2022). "To determine whether NOMO1 has an important role in cell migration, we tested the migration capacity of colon cancer cells in the absence of this gene." (PMID 36011023, 2022).
colorectal tumors (1 paper, 2022). "Thus, we demonstrated that in early-onset colorectal tumors, this gene can be inactivated not only by deletion but also by mutation, which highlights the recurrence of NOMO1 inactivation in the pathogenesis or progression of EOCRC." (PMID 36011023, 2022). "Our in vivo models indicate that the loss of Nomo1 does not directly contribute to the development of colorectal tumors in mice after 20 months of follow-up." (PMID 36011023, 2022).
COVID-19 (1 paper, 2021). A disease caused by infection with severe acute respiratory syndrome coronavirus 2. "Overall, the DCA also showed that Nomo1 is more beneficial in predicting the mortality of the patients with COVID-19 than Nomo2 in a validation cohort." (PMID 34733858, 2021).
Lynch syndrome (1 paper, 2017). An autosomal dominant hereditary neoplastic syndrome characterized by the development of colorectal carcinoma and a high risk of developing endometrial carcinoma, gastric carcinoma, ovarian carcinoma, renal pelvis carcinoma, and small intestinal carcinoma. "These last two, without MMR germline mutation, exhibited homozygous NOMO1 deletion, showing the Lynch syndrome cases all the three possible NOMO1 mutation status." (PMID 28416736, 2017).
myotonic dystrophy type 1 (1 paper, 2025). Steinert disease, also known as myotonic dystrophy type 1, is a muscle disease characterized by myotonia and by multiorgan damage that combines various degrees of muscle weakness, arrhythmia and/or cardiac conduction disorders, cataract, endocrine damage, sleep disorders and baldness. "Interestingly, we identified differential NOMO1 expression in myotonic dystrophy type 1 (DM1) patients, with a positive correlation to dorsiflexion strength in the tibialis anterior muscle (R = −0.59)." (PMID 40663102, 2025).
tumor (5 papers, 2016 to 2025). "We applied the CRISPR/Cas9 technology to delete endogenous NOMO1 in multiple independent cell lines, and used a NOMO1 gut-specific conditional mouse model to study subsequent tumor development." (PMID 36011023, 2022). "We also used a gut-specific conditional knockout (KO) mouse model of Nomo1 to study subsequent tumor development." (PMID 36011023, 2022). "Subsequently, in a Nomo-1 systemic in vivo model, treatment with 3 led to a potent reduction in circulating tumor cells." (PMID 27935476, 2016). "Therefore, our data show the existence of NOMO1 gene pathogenic mutations associated with EOCRC and suggest that this gene may function as a tumor suppressor." (PMID 36011023, 2022). "In a Nomo1 cell line xenograft mouse model implanted in NSG mice, we again noted improved tumor control over empty CAR T cells as well as similar efficacy of aITGB2 CAR T cells and anti-CD33 CAR T cells." (PMID 37904046, 2023). "We analysed NOMO1 in DNA obtained from peripheral blood samples of 13 individuals with EOCRC and homozygous deletion in their tumours." (PMID 28416736, 2017). "To see the effect of the somatic deletion of NOMO1 in EOCRC, and considering that this gene could be a tumor suppressor, we decided to silence Nomo1 expression in the mouse colon cells using a conditional mouse model." (PMID 36011023, 2022). "There was also no subsequent tumor development on deleting Nomo1 using in vivo models." (PMID 36011023, 2022). "Deletion of Nomo1 using in vivo models also did not lead to subsequent tumor development." (PMID 36011023, 2022). "Additionally, a gut-specific conditional NOMO1 KO mouse model revealed no subsequent tumor development in mice." (PMID 36011023, 2022).
colorectal (1 paper, 2022). "Our study is one of the first mechanistic studies of EOCRC biology with a focus on the role of NOMO1 in colorectal carcinogenesis among young individuals." (PMID 36011023, 2022).
NOMO1 also shares sentences with these, for which no sentence is quoted: cancer (2 papers); Anxiety (1); epilepsy (1); glioma (1); Intellectual disability (1); lymphoma (1); myeloid leukemia (1); ovarian carcinoma (1); schizophrenia (1); uterine cancer (1).